RNU6-297P (RNA, U6 small nuclear 297, pseudogene)
Gene: Small nuclear RNA gene on chromosome 14 (48,341,226 to 48,341,332, reverse strand). Ensembl gene ENSG00000207366.
Homologues: Orthologues: chimpanzee U6 (99% identical), macaque U6 (84% identical), pig U6 (77% identical), rat LOC120101196 (72% identical). Paralogues in human: RNU6-393P (87% identical), RNU6-1124P (86% identical), RNU6-31P (86% identical), RNU6-41P (86% identical), RNU6-1060P (85% identical), RNU6-1152P (85% identical), RNU6-144P (85% identical), RNU6-15P (85% identical), RNU6-854P (85% identical), RNU6-1011P (84% identical), RNU6-1075P (84% identical), RNU6-1145P (84% identical), and 1283 more.